ERBB2 (erb-b2 receptor tyrosine kinase 2)
Diseases named in the same sentence as ERBB2 in open-access papers (continued):
Sharing a sentence is not in itself a finding about the gene and the disease.
tumor (continued). "These proteinswere shown to bind and neutralize IFNβ, as well as ErbB2, in tumor celllysates and as a recombinant extracellular domain." (PMID 32742732, 2020). "To understand the mechanism of in utero exposure to BPA-associated tumor promotion in MMTV-erbB2 mice, we examined signaling in the ER and EGFR/erbB2 pathways in premalignant mammary tissues (PND 70) from mice with different in utero treatments." (PMID 32353937, 2020). "In view of the additional ERBB2 mutation, which affects the RAS/RAF/MEK/ERK pathway 30, the tumor board recommended an off-label therapy with combined BRAF- and MEK-inhibition together with the intrathecal application of methotrexate." (PMID 31903155, 2020). "Except for APOB and ERBB2, the remaining genes were the target genes selected above, which were highly related to tumor purity, TME score, immune score, and stromal score." (PMID 33014013, 2020). "The tumor harbored an ERBB2 amplification, and trastuzumab-based therapy resulted in an excellent response, with a necrotic regression of the patient's lung lesion." (PMID 32190395, 2020). "In the ERBB2 pathway, the ERBB2 gene is consistently the highest expressing linear gene among all the three tumor grades but, for circRNA, SOS2 has the highest expression across the grades." (PMID 32670866, 2020). "75% of these tumor samples showed ≥1 (likely) pathogenic mutation, including targetable mutations (e.g. EGFR, BRAF, MET, ERBB2, KIT, PDGFRA)." (PMID 32264863, 2020). "HER2/ERBB2 is a transmembrane protein that induces tumour initiation and progression; therefore, HER2 potentially represents an ideal target, and the safety of CAR-T-HER2 has been confirmed in a phase I trial (NCT01935843)." (PMID 33008426, 2020). "Although sample sizes are too small to draw firm conclusions relative to specific tumour types, T-DXd showed promising antitumour activity in patients with ERBB2-mutant, especially in NSCLC." (PMID 32641355, 2020). "Genomic features, including ERBB2 copy number variation (CNV), total copy number load, and tumor mutation burdens (TMBs), dynamically changed along with the treatment process and correlated with disease progression." (PMID 33377634, 2020). "Equally important, ErbB2 can further improve the ability of tumour cells to migrate and adhere, promote tumour invasion and encourage local and/or distant metastasis." (PMID 32728182, 2020). "Accordingly, we evaluated anti-tumour efficacy in immune-competent transgenic mice, tolerant to human ERBB2, harbouring ectopic, established tumours based on ERBB2-positive LLC1 murine cancer cells." (PMID 32152425, 2020). "Our data support the importance of ErbB2 evaluation, by the immunohistochemical staining of tumor samples after surgery, as a new molecular aspect in CRC mutated patients for personalized therapy selection." (PMID 32066410, 2020). "By this, they brought up a promising DAP10/CD3ζ/CD27 CAR and probed it in T cells versus ErbB2+ tumor cells, both in vitro and in a mouse model." (PMID 32429316, 2020). "TNBC tumors lack estrogen receptor (ERα), progesterone receptor (PR), and HER2 (ErbB2) and exhibit increased glutamine metabolism, a requirement for tumor growth." (PMID 32034133, 2020). "Other investigators used NGS to analyze 54 genes and copy number variants in three genes (EGFR, ERBB2 and MET) on ctDNA of patients with various tumor types." (PMID 32010431, 2020). "ERBIN interacted with the oncogenic ERBB2 tyrosine kinase receptor and was reported as a promoter of tumor growth by ERBB2 and as a tumor suppressor by negatively regulating both Akt and RAF/MEK/ERK signaling." (PMID 32183175, 2020).
tumor (continued). "Our assay was also effective on the detection of CNVs in important oncogenes such as ERBB2 that are equally important for understanding tumorigenesis and deciphering tumour progression mechanisms." (PMID 33033274, 2020). "ErbB2 and WT1 are not only tumor associated antigens for immunological targeting but also biomarkers of cancer cell proliferation and survival, especially GBM." (PMID 32733437, 2020). "Concordant with the efficacy results obtained in our patient, ERBB2 mRNA levels measured in the primary tumor were high (i.e., 2.99)." (PMID 32674482, 2020). "Significant positive associations were observed between the tumor group showing PIWIL4 underexpression and HR+ status (p = 0.0002) and HR+ ERBB2+ molecular subtype (p = 0.0037)." (PMID 33008024, 2020). "We further tested the potential enhancement of the anti-tumor effects of lapatinib in cells transfected with P780-Y781 ERBB2 when AKT signaling was blocked by treatment of perifosine." (PMID 31980423, 2020). "ERBB2 retargeted viruses have been extensively characterized for the specific tropism for ERBB2 positive tumours; fully virulent oHSV with restricted tropism to ERBB2 expressing tumours proved to be efficacious in preclinical models." (PMID 32152425, 2020). "ERBB2-CAR CIK cells showed sustainably migration to distant tumor sites, were capable of penetrating tumor tissues, and showed long-lasting persistence and activity, which we did not observe for WT CIK cells." (PMID 33193388, 2020). "It has been reported that the over expression of ERBB2 was significantly correlated with high grade and advanced stage tumor among a group of NMIBC patients." (PMID 32795296, 2020). "To evaluate combination therapy in vivo, we developed a unique ERBB2+ BC orthotopic nude mouse model of spontaneous metastasis that showed primary tumor growth and clinically relevant distant metastasis to brain, bone, liver, and lung." (PMID 33019652, 2020). "Leucine-rich repeats and immunoglobulin-like domains protein 1 (LRIG1) is a tumor suppressor that regulates various receptor tyrosine kinases, including ERBB2 and other epidermal growth factor receptor family members." (PMID 32448168, 2020). "In patient 9, SMO, NTRK3, IDH2, IGF1R, and CDK12 were also amplified in tumour #1 in addition to ERBB2 amplification." (PMID 31929516, 2020). "ERBB2 expression significantly increased tumor formation in vivo by increasing bile duct obstruction and gross peritoneal metastases." (PMID 32708604, 2020). "The ERBB2 negativity of the tumor was detected by IHC or FISH and was confirmed by NGS for all eight patients." (PMID 32591580, 2020). "Pre-clinical studies using immunocompetent mice as well as highly immunodeficient animals subcutaneously or orthotopically injected with GB cells, revealed that ErbB2 CAR-NK-92 cells were able to hinder the tumor growth and prolong the mice survival." (PMID 32707982, 2020). "Wild-type (WT) CIK cells given at an early stage delayed and eliminated RMS engraftment in 4 of 6 (67%) mice, while ERBB2-CAR CIK cells inhibited initial tumor load in 8 of 8 (100%) mice." (PMID 33193388, 2020). "Immunohistochemistry confirmed that a subset of tumor cells within region #3 express elevated levels of ERBB2 protein." (PMID 33199705, 2020). "The most common BC subtypes were triple-negative (n = 16), HR+/ERBB2− (n = 15), and ERBB2+ (n = 9), with one missing data of the primary tumor." (PMID 32591580, 2020). "ERBB2 receptor retargeting was finally combined to the tumour cell-restricted replication feature for selective infection of ERBB2-positive cells." (PMID 32152425, 2020).
tumor (continued). "Genomic heterogeneity of copy number alteration in tumour #1 and tumour #2 was observed in 7 (33%) of 21 patients including ERBB2 in two patients (patients 9 and 19), FGFR1 in two patients (patients 3 and 13), and FGFR2 in one patient (patient 4)." (PMID 31929516, 2020). "Interestingly, our analysis showed that the AS events of ERBB2 is a favorable prognostic predictor, indicating that depending on the exon deletion site, the resulting splicing variant may play an entirely opposite role in tumor development." (PMID 32793288, 2020). "These NK-92/5.28.ζ cells efficiently lysed ErbB2-expressing tumor cells in vitro and exhibited serial target cell killing." (PMID 32707982, 2020). "The overexpression of EGFR or ERBB2 can promote the proliferation, migration, invasion, and angiogenesis of tumor cells, while suppress their apoptosis." (PMID 33287876, 2020). "ErbB2 is a type of receptor tyrosine kinase, which is known to be involved in tumorigenesis, tumor aggressiveness, and clinical outcome." (PMID 32599712, 2020). "Here, the authors show that the tyrosine kinase c-Src stimulates mitochondrial function to signal energy sufficiency to mTORC1, increasing translation of the PRC2 subunits EZH2 and SUZ12 to support ErbB2-dependent tumours." (PMID 31263101, 2019). "Regarding ERBB2, a significant association was found between the ERBB2 RNA levels (both ICD and ECD) and tumor malignancy (p=0.001, n=27) and the higher ERBB2 expression seems to be related with the lower malignancy grade." (PMID 31301170, 2019). "The downregulation of these genes is in agreement with tumor formation, however the receptor tyrosine kinase ERBB2 is a proto-oncogene, the role of its downregulation by has-miR-25-3p and hsa-miR-552-3p is not known." (PMID 31540229, 2019). "CAR based on antibodies which recognize a shared tumor antigen, such as ERBB2, have led to lethal outcomes." (PMID 31514488, 2019). "A number of immunoRNases on the base of variants of pancreatic human RNase were developed which being fused with antibodies against ErbB2 exhibit strong toxic effects to ErbB2-positive tumor cells." (PMID 31572192, 2019). "Our study also showed the positive expression of HER2/c-erbB-2 was related to the depth of tumor invasion (P < 0.05) and regional lymph node metastasis (P < 0.05)." (PMID 33817143, 2019). "ERBB2/HER2 expression in the WT tumor was also significantly higher than in any of our 19 reference proteomes." (PMID 31805664, 2019). "So in this analysis, we conducted multivariable regression of the 3 modes of ORMDL3 expression only with ERBB2 for both survival and tumor grade data." (PMID 30621577, 2019). "As ErbB2 knockdown can induce apoptotic tumor cell death, we used a siRNA against the ErbB2/HER2 tyrosine kinase in several human tumor cell lines expressing both HER2 and HER3." (PMID 31617560, 2019). "The in vivo anti-tumor activity of ST8176AA1 correlated with the induction of epigenetic modulation in ErbB2+ tumor cells as measured both in vitro and in vivo by increased acetylation of histones and tubulin." (PMID 32039017, 2019). "Overall, p140Cap dampens ERBB2-positive tumor cell progression, impairing tumor onset and growth, and counteracting epithelial mesenchymal transition, resulting in decreased metastasis formation." (PMID 31681758, 2019). "Another agent which targets ERBB2 is scFv(FRP5)-ETA, based on PCa cell lines study it was suggested for treatment of tumours with high HER2 expression." (PMID 30970027, 2019). "NOV-002, the glutathione disulfide mimetic, was shown to suppress tumor cell invasion and metastasis via ErbB2, PI3K, Akt, and RhoA." (PMID 31683902, 2019).
tumor (continued). "Treatment of one chemoresistant patient was changed on the basis of detection of ERBB2 amplification, and this ctDNA-guided decision was followed by significant tumor shrinkage and complete normalization of the cancer antigen 125 tumor marker." (PMID 32914024, 2019). "c-Src ablation significantly decreased the basal, ATP synthesis-coupled and maximal oxygen consumption rates (OCR) of ErbB2+ tumor cells, indicating an overall suppression of respiration." (PMID 31263101, 2019). "The observation of HER2 (ERBB2) amplification in one tumor can have major impact on treatment strategies in one patient, and for the patient #9, after 1 cycle of lapatinib, the patient was switched to palliative care, due to disease progression." (PMID 31740709, 2019). "Examination of the gene expression data from known oncogenes annotated in the Cancer Gene Census with an SI > 0.99 highlighted oncogenes, such as ERBB2, with a known role in breast carcinogenesis." (PMID 30820027, 2019). "The therapeutic benefit of this application was demonstrated by the delivery of ErbB2 siRNA in a HER3-expressing tumor model, resulting in a reduced tumor burden compared to that in experimental controls." (PMID 31617560, 2019). "Commercial lipofection reduced ErbB2 similarly in both tumor lines, whereas HSi reduced ErbB2 only in the HER3+ cells, demonstrating the specificity of HSi-mediated delivery." (PMID 31617560, 2019). "Consistent with CNV data, the ORMDL3 and ERBB2 expression levels were positively correlated for the tumor samples, but with a significant portion of outliers in the upper-left corner." (PMID 30621577, 2019). "High expression of PNCK resulted in increased proliferation, clonal growth, cell cycle progression, and trastuzumab resistance in ERBB2-positive tumor cells." (PMID 30965637, 2019). "We show that down-regulation of Ezh2 expression or inhibition of its methyltransferase activity severely impairs the growth of ErbB2+ tumor cells, while inhibition or genetic ablation of Ezh2 in vivo ablates ErbB2-driven mammary epithelial tumorigenesis." (PMID 31263101, 2019). "On the contrary, PTEN inhibits ERBB2 signalling pathway and is frequently underexpressed or deleted, acting as a tumour suppressor." (PMID 31169290, 2019). "Patients were diagnosed with 29 tumor types and harbored alterations in 43 oncogenes, most commonly ERBB2 (21.3%), PIK3CA (14.1%), and BRAF (8.7%)." (PMID 32914018, 2019). "Detailed analysis of intrinsic-resistant tumours revealed several single-nucleotide variants in KRAS, NRAS, ERBB2, and PDGFRA, which likely confer resistance." (PMID 31653970, 2019). "Here, we report the anti-tumor effect of a new antibody drug conjugate (ADC) delivering a HDAC inhibitor to ErbB2+ solid tumors." (PMID 32039017, 2019).
tumor (continued). "We further show that 1) AR directly transactivates LRIG1 through binding to several AR-binding sites in LRIG1 locus, and 2) LRIG1 dampens ERBB expression in a cell type-dependent manner and inhibits ERBB2-driven tumor growth." (PMID 31792211, 2019). "In three cases where tumour tissue sequencing failed, amplifications in ERBB2, FGFR2, EGFR, and CCND1 were identified in ctDNA." (PMID 31137920, 2019). "Consistent with PCNA expression, ERBB2 protein expression shows a significant decrease in tumor tissues of the IT group compared to the INT group (p<0.05)." (PMID 32695310, 2019). "Higher Ras-MAPK and PI3K-Akt signaling activity is detected in ERBB2 overexpressing tumor cells, which show stronger cell proliferation ability." (PMID 32039169, 2019). "ERBB2 amplification was detected by sequencing in 1 tumour with an intestinal subtype, and this was confirmed by IHC staining 3+ and also by FISH." (PMID 30837681, 2019). "The patient’s primary tumor and the derived PDX had activating PIK3CA E545K and ERBB2 L755S mutations and we previously reported that this PDX is resistant to irinotecan alone." (PMID 31627299, 2019). "The TCGA CIN subtype was also notable for frequent EGFR amplification, including Erbb2 (HER2) (24% in CIN tumours in the TCGA cohort), and, accordingly, HER2 overexpression was seen exclusively in our CIN tumours (8/48, 16.7%)." (PMID 31790410, 2019). "The immunoreactivity and binding selectivity of ST8176AA1 was tested by ELISA on recombinant ErbB2 extracellular domain coated plates and by cytofluorimetry on ErbB2 expressing tumor cell lines, respectively." (PMID 32039017, 2019). "Copy number variation of molecular targets, as assessed in both tumour and cfDNA, has been shown to impact on therapeutic targeting of ERBB2, FGFR, and EGFR, with high level amplifications being associated with more favourable responses." (PMID 31137920, 2019). "It should be noted that copy gains of EGFR, FGFR1, MET, and ERBB2 have already been reported to be predictive markers for certain tumor types." (PMID 31480645, 2019). "GPAA1 expression, ERBB2 expression, age, tumour size, vascular invasion, TNM stage, lymphatic metastasis, and perineuronal invasion were significantly correlated with overall survival." (PMID 31118109, 2019). "Intravenous delivery (via tail vein) of HSi in mice bearing human xenografts of HER3+ tumors significantly reduced tumor growth rates, corresponding to a substantial reduction of ErbB2." (PMID 31617560, 2019). "In summary, lapatinib exhibited cytotoxic properties on ErbB1/ErbB2 expressing cell lines, with jejunal cells being more sensitive to lapatinib compared to tumour cells." (PMID 31905843, 2019). "Combination treatment also significantly decreased the expression of the proliferation maker Ki67 at the 14-day time point, indicating that only the combination of these two drugs reduced the growth rate of this otherwise single-agent-resistant ERBB2+ tumour." (PMID 30898150, 2019). "Clinically, 28 patients were diagnosed with HER2 overexpression, of whom 26 (92.86%) had detectable ERBB2 amplification in their tumor DNA." (PMID 30672098, 2019). "Then, NF-kB activity enhances ErbB2-mediated murine mammary tumorigenesis by stimulating tumor angiogenesis." (PMID 30621730, 2019). "We characterize the model in the presence of two of the most frequent oncogenic drivers—Kras and ERBB2—and provide evidence that the tumor histology is highly dependent on the driver oncogene." (PMID 31795490, 2019). "A study of matched normal, early neoplasia and carcinoma from a cohort of 25 women identified elevated expression of ERBB2, FOXA1, and GATA3." (PMID 31248446, 2019). "One study demonstrated that TNF-α secreted by tumor cells stimulated the growth of malignant mammary epithelial cells, which contributed to mammary tumorigenesis in neu/erbB2 transgenic mice." (PMID 31341911, 2019).